ICAM1 (intercellular adhesion molecule 1)
Diseases named in the same sentence as ICAM1 in open-access papers (continued):
Sharing a sentence is not in itself a finding about the gene and the disease.
cancer (continued). "ICAM-1 is a member of the immunoglobulin superfamily of proteins expressed in all leukocytes and on the surface of many cancer cell types, which shows altered expression in malignant diseases and involved in the process of cancer metastasis." (PMID 38554213, 2024). "Immunohistochemical studies revealed that TNBC cancer tissues expressed more ICAM-1 than paracancerous tissues; however, there are insufficient reports in the existing literature." (PMID 38799250, 2024). "γδ T cells stimulate the upregulation of MHC class I and CD54/intercellular adhesion molecule-1 (ICAM-1) expression in cancer stem cell (CSC)-like cells, thereby enhancing the susceptibility of CD8+ T cells to antigen-specific killing." (PMID 39253082, 2024). "The ICAM-1 level of the cancer control rats (582.95 ± 7.17 pg/mL) was greater than that of the negative control (361.55 ± 2.19 pg/mL) by about 37.98% (p ≤ 0.05)." (PMID 39338293, 2024). "Esm1 recombinant protein decreased T cell adhesion to ICAM-1, and cancer cell medium from Esm1 overexpression group inhibited T cell adhesion compared to Bcl6 knockout control group." (PMID 38956432, 2024). "Intercellular adhesion molecule 1 (ICAM-1; CD54), a cell surface glycoprotein, is known to be involved in cancer metastasis." (PMID 39132161, 2024). "We first compared ICAM-1 expression level in 17 different cancer types by analyzing the normalized mRNA expression data from The Cancer Genome Atlas (TCGA) database." (PMID 39168965, 2024). "The rate of ICAM-1 expression was higher in advanced stages of cancer, especially in cases with lymph node metastasis and liver metastasis." (PMID 39766041, 2024). "These associations highlight the complexity of the immune landscape in cancer progression and the potential of ICAM1 as a prognostic biomarker." (PMID 39767561, 2024). "So, blocking EGFR or intercellular adhesion molecule-1 (ICAM1) antibody neutralization in TAMs decreased cancer cell migration in mice." (PMID 39003350, 2024). "In this study, we demonstrate that cell surface-expressing ICAM-1 provides anti-apoptotic signal to NSCLC cells through interacting with cancer cell-derived FGG." (PMID 39168965, 2024). "This study observed that ICAM‐1 expression was higher in the anti‐PD‐1‐responsive mouse cancer models." (PMID 37097643, 2023). "Cannabinoids can also modulate cancer progression via the increase of intercellular adhesion molecule-1 (ICAM-1) expression, decreasing metalloproteinase expression and modulating several other extracellular matrix components." (PMID 37521486, 2023). "Pan-cancer expression analysis revealed that ICAM1 is expressed differentially in cancer types, and ICAM1 expression was up-regulated in TNBC." (PMID 37671167, 2023). "Extending this study to other types of human cancers is crucial for a comprehensive understanding of ICAM‐1." (PMID 37097643, 2023). "In particular, increased expression of the channel was detected in more aggressive cells where it also regulates ICAM-1 dependent cell-cell adhesion between endothelial and cancer cells." (PMID 37942486, 2023). "Given the major role of ICAM-1 in the development of numerous diseases, particularly inflammatory conditions and cancers, there has been a substantial research effort directed at the development of therapeutics that target the protein." (PMID 37237555, 2023). "It has been suggested that ICAM-1 acts as a facilitator of cancer cell spread through the recruitment of inflammatory cells that release stimulating factors for cell proliferation, angiogenesis, and invasion." (PMID 36906717, 2023). "Uveal melanoma has also been identified as a cancer type with high ICAM-1 expression, particularly in the metastatic setting." (PMID 36651961, 2023). "ICAM1-mediated adhesion on cancer cells is a prerequisite for their interaction with T cells through LFA-124." (PMID 36871040, 2023). "We furtherly explained how LKB1 mutant cancer cells escape immune attack by circumventing ICAM1-driven immune response." (PMID 36871040, 2023).
cancer (continued). "ICAM-1 can also promote or protect against cancer, depending on the type of cancer and the cell populations that are producing it." (PMID 37237555, 2023). "Intracellular adhesion molecule 1 (ICAM1, also known as CD54) is a multifunctional cell surface protein of the immunoglobulin superfamily which is overexpressed in cancers." (PMID 37880707, 2023). "The neutrophil ITGAM/ICAM-1 mediated the adhesion of lipopolysaccharide-activated neutrophils to the cancer cells." (PMID 37006265, 2023). "Research has indicated that a reduction in ICAM1 expression results in diminished cancer cell adhesion and promotes distant metastasis of cancer cells." (PMID 37671167, 2023). "TCGA data analysis showed upregulation of expression of ICAM-1 cleavage related metalloproteases in different human cancers." (PMID 37732732, 2023). "From an unbiased profile through scRNA sequencing, we discovered that impairment of ICAM1-mediated cancer cell-T-cell adhesion and interactions plays a crucial role in the formation of T-cell deficient TME." (PMID 36871040, 2023). "In cancer, ICAM-1 was reported to promote cancer cell migration, invasion, as well as the increase in mesenchymal marker expression." (PMID 36675033, 2023). "ICAM1+ neutrophils are generally considered to have anti-cancer effects while CXCR4+ neutrophils exert the opposite effect." (PMID 37644468, 2023). "Altogether, these results highlight the complexity of the roles of ICAM-1 in its ability to act both in favor of the cancer and of the host." (PMID 37237555, 2023). "Following selinexor incubation, we observed no significant change in the surface expression of ULBP-1, ULBP-2/5/6, MIC-A/B, CD54 (ICAM-1), B7-H6, or externalised calreticulin (ecto-reticulin), recently identified as the cancer associated ligand for NKp46." (PMID 37528310, 2023). "Particularly, cancer cells in KL versus K showed impaired interaction with T cells relating to ICAM1-mediated T-cell adhesion and recruitment." (PMID 36871040, 2023). "Pre-treatment of CD8+ T cells with anti-CD11a antibodies (LFA-1 blockade), reduced CD69 and CD44 expressions on T cells after co-culture experiments, indicating that ICAM1 on cancer cells mediates the interaction with T cells by binding to LFA-1." (PMID 36871040, 2023). "Through increased IL-1β secretion, macrophage coculture enhances the expression of intercellular adhesion molecule 1 (ICAM1), which promotes the stemness property and the formation of polypoid giant cancer cells to increase the resistance of HNSCC to DTX." (PMID 38001888, 2023). "Cells pre‐treating c‐Jun siRNA abolishes CX3CL1‐induced cell migration and ICAM‐1 expression, demonstrating that c‐Jun phosphorylation mediates CX3CL1‐induced cancer metastasis and ICAM‐1 expression." (PMID 37082943, 2023). "Expression of adhesion molecule ICAM1 also predicts poor prognosis for several cancer types, closely mimicking the effects observed for the IL1R1 and IL6R genes." (PMID 37006265, 2023). "A cytotoxicity assay of cancer cells co‐cultured with CD8+ T cells revealed that ICAM‐1 depletion diminished CD8+ T cell‐mediated CT26 cell killing." (PMID 37097643, 2023). "Expression of ICAM1 and ICAM-1 cleavage related metalloproteases is upregulated in human cancers and associated with poor clinical outcome." (PMID 37732732, 2023). "ICAM1 is reported to involve different cancer kinds, such as ovarian cancer, colorectal, renal cell carcinoma, and prostate." (PMID 37671167, 2023). "ICAM-1 has an important role to play as a facilitator or target of immunological therapies for cancer, especially for hematological malignancies, although it is being increasingly explored as a target in solid tumors as well." (PMID 37237555, 2023). "STAT3 is regarded as a therapeutic target in many cancers and regulates cyclinD1, c-Myc, Bcl-2, survivin and ICAM-1, related to cell proliferation, survival, migration, invasion, stemness, immunosuppression and angiogenesis." (PMID 37147297, 2023).
cancer (continued). "In all experimental results, cancer cells expressing c-MET/ICAM-1/SRC together showed the highest malignancy, and p-SRC activity was also upregulated." (PMID 35487888, 2022). "Here, we review recent advances showing that the adhesion between CAR T cells and cancer cells from solid tumors strengthens over time in an IFNγ- and ICAM-1-dependent manner, resulting in CAR T cell-mediated killing." (PMID 36189315, 2022). "MMPs and ICAM-1 are master regulators that sustain the migration properties in various cancer types." (PMID 35799889, 2022). "Secondly, the importance of ICAM-1 expression on cancer cells for CAR T-cell activation was also revealed in a CRISPR-based screen performed in a multiple myeloma cell line." (PMID 36189315, 2022). "ICAM-1 was expressed on cancer cells (47/59, 79.66%), stromal endothelium (46/59, 77.97%), or both epithelium and endothelium (40 of 59, 67.8%)." (PMID 35630004, 2022). "The up-regulation of ICAM-1 has been described in various types of cancer and can promote cancer metastasis." (PMID 36497262, 2022). "Most studies have demonstrated that ICAM-1 regulates cancer metastasis via the binding receptor, LFA-1, which can activate numerous pathways." (PMID 36016615, 2022). "Most studies have revealed that ICAM-1 plays an important role in the progress and metastasis of many cancers." (PMID 36016615, 2022). "ICAM-1 primarily acts as an adhesive molecule; however, it can also promote metastasis and angiogenesis and weaken the immune response in cancer cells." (PMID 35487888, 2022). "ICAM-1 has also been studied in cancer cells, where they found that an upregulation of ICAM-1 increased cell survival." (PMID 35572574, 2022). "Several genes associated with cancer cell motility, including SEMA5A, PDGFRB, TGFB2, CXCR4, SNAI1, ICAM1, and NEDD9, were decreased in shGPR81 cells." (PMID 35428832, 2022). "ICAM-1 expression in cancer cells was noted in 47 cases (79.66%) and in endothelial cells in 46 cases (77.97%); in 40 cases (67.8%) the expression was observed in both compartments." (PMID 35630004, 2022). "Macrophage coculture induced expression of intercellular adhesion molecule 1 (ICAM1), which promotes stemness and the formation of polyploid giant cancer cells, thereby reducing the efficacy of DTX." (PMID 36264639, 2022). "Inflammatory cells in the TME promote cancer cell metastasis through the release of several adhesion molecules and chemokines, such as intercellular cell adhesion molecule-1 (ICAM-1) and matrix metalloproteinases (MMPs)." (PMID 35799889, 2022). "The importance of ICAM-1 expression on cancer cells for CAR T-cell activation was revealed in a CRISPR-based screen performed in a multiple myeloma cell line." (PMID 35681548, 2022). "Further, ICAM-1 was also found to be expressed both on cancer epithelium and endothelium of adjacent stromal vessels, thus we decided to assess the correlation between EGFL7 and ICAM-1 matched according to the source of origin." (PMID 35630004, 2022). "Intercellular adhesion molecule-1 (ICAM-1) is a surface molecule expressed by mesothelial cells, cancer cells and endothelial cells." (PMID 36614904, 2022). "In 2021, Huiping Liu found that the expression of inter–cellular adhesion molecule 1 (ICAM1) increased 20 times in pulmonary metastatic cancer cells compared with non–metastatic cancer cells." (PMID 36059616, 2022). "We next verified that the relapse-free survival of luminal B cancer patients is significantly prolonged by an elevated ICAM-1 expression." (PMID 35911772, 2022). "Overexpression of HPSE can contribute to the aggregation of CTCs, and induce FAK signaling pathway and ICAM1–dependent cell adhesion, finally promoting the aggregation of cancer cells in the blood vessels." (PMID 36059616, 2022). "Since STAT3 is known to directly regulate ICAM-1 expression in various cancer types, chromosome immunocompatibility (CHIP) assay was performed to investigate this role of STAT3 in CRC." (PMID 35487888, 2022).
cancer (continued). "ICAM1 significantly encourages the adhesion of inflammatory sites, regulates cancer development and metastasis, and modifies the immune response." (PMID 35341150, 2022). "At the same time, ICAM1 on cancer cells and β2 integrin on neutrophils interact with each other to mediate their aggregation." (PMID 36059616, 2022). "The expression of ICAM1 and its soluble part is more obvious during the inflammatory response, chronic diseases, and many malignant tumors." (PMID 35341150, 2022). "It was observed that cannabinoids induced ICAM-1 expression, resulting in the activation of lymphokine-activated killer cells against the cancer cell lines." (PMID 36437760, 2022). "Findings of studies on other malignant tumors suggest that ICAM-1 contributes to carcinogenesis by at least two mechanisms." (PMID 35630004, 2022). "In a rescue experiment, more cytotoxicity was observed in EGFR-CAR T cells when ICAM-1 was overexpressed on IFNγR1-KO cancer cells." (PMID 36085295, 2022). "Based on the median ICAM-1 score in cancer cells, we dichotomized the group into a high expressing subgroup (22 cases, 37.29%) and a low expressing subgroup (37 cases, 62.71%)." (PMID 35630004, 2022). "ICAM-1 is an important regulator of cell–cell interactions and recent studies have shown that it promotes malignancy in several carcinomas." (PMID 35487888, 2022). "In mammals, previous studies have shown that LPS cannot induce ICAM-1 expression in the intestinal epithelial cells, but enhanced ICAM-1 expression in the abnormal cells, such as senescent endothelial cells and cancer cells." (PMID 34489953, 2021). "The immunofluorescence analysis showed that MAs upregulated vimentin expression in all four cell types, whereas the induction of ICAM-1 expression was evident only in cancer cells." (PMID 33921783, 2021). "We demonstrated that ICAM-1 is localized within the cancer-γδ T immune synapse along with other classical immune synapse proteins, including LFA-1 and linker for activation of T cells (LAT)." (PMID 33846331, 2021). "ICAM-1 was also prevalent in U87MG, which is associated with invasion and metastases in several types of cancer." (PMID 34207434, 2021). "Following initial adhesion, the interaction between αMβ2 integrin on neutrophils and ICAM1 on breast CTCs induces cancer cell TEM." (PMID 33498251, 2021). "In the same paper they suggest ICAM-1 as a potential target for cancer treatment by incrementing lymphocyte migration to the lymph nodes." (PMID 34430923, 2021). "To further validate LFA1-P-mediated targeting and drug delivery into ICAM-1-overexpressing cancer metastasis in vivo, we established a lung metastatic model of 4T1 with our previous method." (PMID 35056985, 2021). "Collectively, ICAM1 has potential to become an import immunotherapeutic target for cancer patients especially via adoptive cellular therapy using chimeric antigen receptor (CAR) T cells." (PMID 34408980, 2021). "All these 4 clusters were characterized by cancer stem-like cell phenotypes; Cluster 10 and 18 exhibited high levels of vimentin, ER-β and ICAM-1, positive expression of PD-L1." (PMID 34771607, 2021). "Secreted factors in conditioned medium from head and neck squamous cell lines promote the expression of CD54/ICAM-1 in MSCs, an event that is relevant in the interplay among MSCs, immune cells, and cancer cells." (PMID 34680425, 2021). "ICAM1 can also be shedded from the endothelium into the blood stream and interact with cancer cells to enhance their pro-metastatic potential." (PMID 34073394, 2021). "Recently, Haustein and co-workers showed that Met-F-AEA treatment of lung cancer cells led to ICAM-1 upregulation and increased their susceptibility to the cytolytic action of LAK cells, suggesting a novel anti-cancer action mode of cannabinoids." (PMID 34943903, 2021). "MAC-1 binds to its counter receptor ICAM-1, which in mixed cultures was simultaneously induced on the surface of cancer cells." (PMID 35052746, 2021).